TEC (tec protein tyrosine kinase)
Description:
Non-receptor tyrosine kinase that contributes to signaling from many receptors and participates as a signal transducer in multiple downstream pathways, including regulation of the actin cytoskeleton. Plays a redundant role to ITK in regulation of the adaptive immune response. Regulates the development, function and differentiation of conventional T-cells and nonconventional NKT-cells. Required for TCR-dependent IL2 gene induction. Phosphorylates DOK1, one CD28-specific substrate, and contributes to CD28-signaling. Mediates signals that negatively regulate IL2RA expression induced by TCR cross-linking. Plays a redundant role to BTK in BCR-signaling for B-cell development and activation, especially by phosphorylating STAP1, a BCR-signaling protein. Required in mast cells for efficient cytokine production. Involved in both growth and differentiation mechanisms of myeloid cells through activation by the granulocyte colony-stimulating factor CSF3, a critical cytokine to promoting the growth, differentiation, and functional activation of myeloid cells. Participates in platelet signaling downstream of integrin activation. Cooperates with JAK2 through reciprocal phosphorylation to mediate cytokine-driven activation of FOS transcription. GRB10, a negative modifier of the FOS activation pathway, is another substrate of TEC. TEC is involved in G protein-coupled receptor- and integrin-mediated signalings in blood platelets. Plays a role in hepatocyte proliferation and liver regeneration and is involved in HGF-induced ERK signaling pathway. TEC also regulates FGF2 unconventional secretion (endoplasmic reticulum (ER)/Golgi-independent mechanism) under various physiological conditions through phosphorylation of FGF2 'Tyr-215'. May also be involved in the regulation of osteoclast differentiation.
Synonyms: PSCTK4
Tractability: Small molecule: an approved drug acts on it; a high-quality ligand is known; it belongs to a druggable protein family. Antibody: its Gene Ontology location is reachable by antibodies, with high confidence; UniProt places it where antibodies can reach, with medium confidence; the Human Protein Atlas places it where antibodies can reach. PROTAC: it is named in the literature on targeted protein degradation; ubiquitination databases record sites on it; its protein half-life has been measured; a small molecule that binds it is known.
Target class: TK protein kinase group; Kinase; Protein Kinase; Enzyme; Tyrosine protein kinase Tec family
Gene: Protein-coding gene on chromosome 4 (48,135,783 to 48,269,858, reverse strand). Ensembl gene ENSG00000135605.
Subcellular location: Cytoplasm; Cell membrane; Cytoplasm, cytoskeleton
Subcellular location (Human Protein Atlas): Plasma membrane
Pathways (Reactome):
Immune System: FCERI mediated Ca+2 mobilization; Interleukin-3, Interleukin-5 and GM-CSF signaling
Signal Transduction: Signaling by SCF-KIT
Gene Ontology:
Molecular function: non-membrane spanning protein tyrosine kinase activity; protein binding; phospholipid binding; ATP binding; protein kinase activity; protein tyrosine kinase activity
Biological process: B cell receptor signaling pathway; integrin-mediated signaling pathway; regulation of platelet activation; adaptive immune response; intracellular signal transduction; protein phosphorylation; T cell receptor signaling pathway; tissue regeneration
Cellular component: cytoskeleton; plasma membrane; cytosol; cytoplasm
Genetic constraint (gnomAD): Loss-of-function variants: 58 observed, 81.06 expected, observed/expected ratio (o/e) 0.72, 90% interval 0.58 to 0.89. The upper end of that interval is the gene's LOEUF score, 0.89, which puts it in group 3 of 6, group 1 being the genes least tolerant of losing a copy. Missense variants: 551 observed, 699.21 expected, observed/expected ratio (o/e) 0.79, 90% interval 0.73 to 0.85. Synonymous variants: 218 observed, 231.07 expected, observed/expected ratio (o/e) 0.94, 90% interval 0.84 to 1.05.
Homologues: Orthologues: chimpanzee TEC (99% identical), macaque TEC (99% identical), dog TEC (96% identical), pig TEC (96% identical), rabbit TEC (95% identical), rat Tec (95% identical), mouse Tec (95% identical), guinea pig TEC (95% identical), tropical clawed frog tec (76% identical), zebrafish tec (61% identical). Paralogues in human: ITK (57% identical), BTK (55% identical), BMX (48% identical), TXK (48% identical), ABL2 (31% identical), ABL1 (30% identical), FYN (30% identical), BLK (30% identical), FGR (29% identical), FRK (29% identical), SRC (29% identical), YES1 (29% identical), and 20 more.
Diseases named in the same sentence as TEC in open-access papers:
TEC is named in the same sentence as 3 diseases in open-access papers, as found by Europe PMC text mining. Sharing a sentence is not in itself a finding about the gene and the disease.
TEC shares sentences with these, for which no sentence is quoted: cancer (1 paper); colitis (1); psoriasis (1).